FGF2 (fibroblast growth factor 2)
Diseases named in the same sentence as FGF2 in open-access papers (continued):
Sharing a sentence is not in itself a finding about the gene and the disease.
tumor (continued). "Synstatin, a mimetic peptide, inhibits the signaling complex formation between SDC-1, IGF1R, and integrin αvβ3 and attenuates HS-dependent angiogenic VEGF and FGF2 signaling, and blocks tumor angiogenesis in vivo." (PMID 36551220, 2022). "The depletion of TAMs markedly decreased the metastasis rate of both vector and FGF-2 tumor–bearing mice." (PMID 35439170, 2022). "Fibroblast growth factor 2 (FGF2) is a tumor cell survival factor that belongs to a subgroup of extracellular proteins lacking N-terminal signal peptides." (PMID 35433697, 2022). "FGF2 also plays a critical role as a tumor cell survival factor blocking programmed cell death through both autocrine and paracrine signaling." (PMID 35348113, 2022). "FGF-2 tumor–bearing mice showed elevated CTC levels and increased tumor clones from blood culture, and approximately 80% of them developed pulmonary metastasis." (PMID 35439170, 2022). "Genetic and pharmacological targeting the FGF-2/FGFR1 signaling or depletion of pericytes obliterates tumoral CXCL14 expression in FGF-2–expressing tumor–bearing mice." (PMID 35439170, 2022). "Genetic knockdown of FGF-2 in NPC tumor cells reduced tumor angiogenesis, enhanced AAD sensitivity, and reduced pulmonary metastasis." (PMID 35985991, 2022). "Growth factors and cytokines secreted by non-immune cells of the tumor microenvironment with stimulatory effects on tumor growth include FGF-2, among others." (PMID 35619925, 2022). "FGF2 is a member of fibroblast growth factor family, which has been reported to participate in several tumor-related pathways, such as cell growth, differentiation, and angiogenesis." (PMID 35401707, 2022). "Neutrophils release the factors of tumour-related angiogenesis, such as vascular endothelial growth factor, angiopoietin-1 and fibroblast growth factor-2." (PMID 35743468, 2022). "We extracted an equal amount of scrambled control- and FGF2 shRNA–transfected 5-8F tumor tissues and performed FACS analysis of various immune cells." (PMID 35439170, 2022). "To investigate this mechanistically, we conducted in vitro T-cell killing assays, which demonstrated that pretreatment of tumor cells with FGF2 and PDGF reduced the cytotoxicity of CD8+ T cells in a SHP2-dependent manner." (PMID 36969745, 2022). "CD44 binding to FGF2 specifically increases FGF2-mediated proliferation, migration and survival of tumor and endothelial cells, thereby increasing tumor growth and metastasis." (PMID 35936713, 2022). "Overexpressing FGF-2 facilitated tumor growth, proliferation phenotypes, angiogenesis, and metastasis in these mouse tumor models, further supporting its angiogenic role and its functional consequences in the TME." (PMID 35985991, 2022). "Our qPCR results confirmed that the average expression level of FGF2 was significantly higher in ESCC specimens than in their adjacent non-tumor counterparts (P < 0.001)." (PMID 35941662, 2022). "Consistent with our findings, recent studies have suggested that fibroblast growth factor 2 depletion can lead to increased T-cell recruitment, enabling tumor regression." (PMID 35764641, 2022). "The VEGF/VEGFR, the angiopoietins (ANGPT) and their tyrosine kinase receptors (Tie2/Tek), or molecules mediating tumor angiogenesis, like the fibroblast growth factor (bFGF/FGF2) and platelet-derived growth factor-B (PDGF-B), have been the main targets." (PMID 35664746, 2022). "While most of its physiological functions are shared with FGF1, FGF2 plays a vital role in tumor-induced angiogenesis, contributing to tumor growth." (PMID 35784465, 2022). "Genetic knockdown of FGF2 or genetic depletion of tumoral pericytes blocked CXCL14 expression and tumor-associated macrophage (TAM) infiltration." (PMID 35439170, 2022). "In particular, FGF2 is overexpressed in imatinib-resistant GIST cells as well as in tumor samples from imatinib-resistant GIST." (PMID 34204560, 2021).
tumor (continued). "FGF1 and FGF2 appear to have the greatest roles in cancer as both of them can act as tumor growth factors and thus increase tumor growth and invasion." (PMID 33799622, 2021). "Nevertheless, we checked the expression of Fgf2 and Vegfa in tumor samples and in 4T1 cells treated with AuNPs in vitro." (PMID 33653008, 2021). "This molecular inhibits the proliferation and migration of HCC cell lines and blocks angiogenic signals in the mouse model, corroborating the role of FGF2 in tumor growth and vascularization." (PMID 33802841, 2021). "Previous studies have shown that both VEGF and FGF2 act synergistically in tumor-driving angiogenesis." (PMID 34830951, 2021). "Various cancer studies reported miR-497-5p as a tumor regulator, potentially through its regulatory effects on NF-κB and FGF-2 signaling." (PMID 34502118, 2021). "It was supported that blocking FGF2 with vascularization inhibitors leads to a significant reduction in tumor size." (PMID 33935756, 2021). "FGF2 is one of the most potent angiogenic stimulators in tumor growth and is known to be a stronger angiogenic factor than VEGF, i.e., the current therapeutic target in GBM." (PMID 34790962, 2021). "Findings show that FGF2 is secreted from CAFs and contributes to tumor cell growth by stimulating synthesis of more collagen and the secretion of inflammatory cell-recruiting cytokines via CAFs expressed TGFβ, MMP7, and FGF9." (PMID 34203430, 2021). "FGF2 expression by tumor vasculature pericytes has also been identified as a mechanism of anti-vascular endothelial growth factor receptor (VEGFR) resistance." (PMID 34068954, 2021). "FGF-2/FGFR system contributes to cancer progression by autocrine/paracrine stimulation of tumor cell proliferation and angiogenesis." (PMID 33718141, 2021). "In vitro and in vivo evidence indicates that HS6ST2 is essential for vascular development and plays an important role in tumor angiogenesis due to its interactions with several angiogenic growth factors, including FGF2, VEGF, IL8, and IL6, among others." (PMID 34944958, 2021). "Here, we showed that the stiffness microenvironment activates a CD36/AKT/E2F3 mechanosignaling to modulate tumor-promoting factor FGF2 expression." (PMID 34873170, 2021). "Tumor cells and fibroblasts can secret a variety of cytokines and growth factors, including il-6, bFGF/FGF2, TGF-β1 and HGF, which triggers the transdifferentiation of nontransgenic normal fibroblasts (NFSs) to CAFs." (PMID 34563186, 2021). "The antitumor effect of 3F12E7 anti-FGF2 scFv was evaluated in the B16-F10 experimental tumor model." (PMID 33446839, 2021). "To summarize, the present study reported a fully human ds-Diabody against FGF-2 expressed in Pichia pastoris, which possessed high antigen binding ability and anti-tumor activity in vitro and in vivo through inhibiting angiogenesis." (PMID 33718141, 2021). "In tumor endothelial cells, FGF2 switches the TGFβ endothelial-to-myothelial program to differentiate into active fibroblastic cells through activation of E26 transcription factor ELK1, a downstream target of ERK1/2 activation." (PMID 34068954, 2021). "The obtained scFv succeeded in specifically recognizing FGF2 in tumor extracts and inhibiting experimental tumor growth similar to the corresponding full-length IgG antibody counterpart." (PMID 33446839, 2021). "Functionally, the 3F12E7 scFv preparations specifically recognize FGF2 and inhibit tumor growth similar to the corresponding full-length IgG counterpart in an experimental model." (PMID 33446839, 2021). "FGF-2 neutralization with monoclonal antibodies in HCC xenograft mouse models has demonstrated reduced tumor growth." (PMID 34638361, 2021). "Elevated concentrations of FGF-2 and increased tumor microvascular density are potential markers of worse overall prognosis and abbreviated progression-free survival." (PMID 33718141, 2021).
tumor (continued). "Recently, a novel therapeutic strategy for cancers is raised by virtue of overexpression of PTX3 which inhibits fibroblast growth factor-2 (FGF2) dependent tumor growth." (PMID 33746606, 2021). "For example, when heparanase cleaves HS from perlecan in the basement membrane it releases bound FGF2, which promotes angiogenesis, wound healing and tumour formation." (PMID 33450893, 2021). "Monoclonal antibody (GAL-F2) blockade of FGF2 also restricted tumor growth and normalized vasculature, suggesting an FGF2-dependent mechanism through which TANs contribute to CRLM." (PMID 34944826, 2021). "Antibodies against FGF2 and FGF8 have also shown promising results in inhibiting tumour progression and angiogenesis A human single-chain variable fragment (ScFvs; 1A2) that binds to human FGF2 was identified via screening of a human scFv phage library." (PMID 34830836, 2021). "Stiffness induces E2F3 nuclear transcription of FGF2, a tumor-promoting factor, to promote HCC growth and metastasis." (PMID 34873170, 2021). "In this study, we mainly reported the production of ds-Diabody against FGF-2 by high density fermentation in recombinant Pichia pastoris and its effects on tumor angiogenesis and tumor growth in vitro and in vivo." (PMID 33718141, 2021). "FGF1 and FGF2 are correlated with increased sinusoidal capillarization, which is involved in tumor angiogenesis." (PMID 33935756, 2021). "The biological effects of FGF2 are exerted through the formation of ternary FGF2-heparin-FGF receptor complexes in several cells in the tumor microenvironment, including endothelial and neoplastic cells." (PMID 33446839, 2021). "FGF-2 promotes cell resistance in both irradiated normal and tumor tissues, notably through the downregulation of apoptosis." (PMID 34407878, 2021). "In our study, it was shown that the expression of CD31, a marker of vascularity, was decreased obviously in tumor tissues treated by ds-Diabody against FGF-2." (PMID 33718141, 2021). "P‐EVs also enhance the formation of new blood vessels during tumor growth via concerted action of FGF‐2, VEGF, and a lipid factor." (PMID 33345458, 2021). "FGF-2 is an important tumor angiogenesis factor, and targeting FGF-2 can inhibit tumor angiogenesis and tumor growth." (PMID 33718141, 2021). "The crystal violet staining of GIST T-1 cultures revealed that FGF-2 effectively rescued the proliferation of tumor cells treated with IM." (PMID 32599808, 2020). "In this study, we aimed to deliver FGF2 using SPIONs to inhibit the activation of PSCs and thereby inhibit the stroma-induced tumor cell growth." (PMID 31911892, 2020). "Overall our work defines FGF2 as a key modulator of macrophage polarisation in tumours and demonstrates that FGF2, as well as other factors which regulate macrophage activity, can be targeted during radiotherapy." (PMID 32792542, 2020). "Most importantly, IM promotes the malignant behavior of IM-resistant GISTs by stimulating their migration, invasion, and colony formation of tumor cells via the activation of the FGF-2/FGFR autocrine loop." (PMID 32599808, 2020). "Expectedly, E0771-FGF-2 tumors became antiangiogenic resistant in response to anti-VEGF monotherapy since FGF-2 also significantly augmented tumor angiogenesis and compromised the anti-VEGF sensitivity." (PMID 32709869, 2020). "In conclusion, this study demonstrates a novel strategy to target FGF2 to tumor stroma using SPIONs and thereby induce the efficacy of gemcitabine by reducing the stroma barrier." (PMID 31911892, 2020). "When using a different measure, perfused vessel volume, to evaluate vascularity, MC38 tumour vascularity was unaffected by anti-FGF2 antibody, but was reduced after irradiation." (PMID 32792542, 2020). "Dependency on the FGF2 signaling pathway for tumor angiogenesis then emerges as the number of tumor vessels covered with pericytes, which overexpress FGF2, increases." (PMID 32076044, 2020).
tumor (continued). "Fibroblast growth factor 2 signal is an imbalance in cancer cells and a key tumor promoter in the tumor microenvironment." (PMID 32547947, 2020). "In conclusion, this study presents a novel approach to target FGF2 to tumor stroma using SPIONs and thereby enhancing the effect of gemcitabine as demonstrated in the complex 3D tumor spheroid model." (PMID 31911892, 2020). "Here we show that FGF-2 modulates tumor vessels by recruiting NG2+ pricytes onto tumor microvessels through a PDGFRβ-dependent mechanism." (PMID 32709869, 2020). "The expression of VEGFA, as well as FGF-2, is also triggered by the fibronectin extra-domain B, the tumor-specific isoform of fibronectin, and was shown to increase esophageal cancer vascularization." (PMID 32456248, 2020). "Subsequent studies show OAds under CXCR4 transcriptional targeting and fibroblast growth factor-2 (FGF2) translational control are significantly more specific for tumor tissue than normal breast tissue." (PMID 32155969, 2020). "In the present study, we demonstrate for the first time that targeting of FGF2 using SPIONs reduces the tumor stroma and potentiates the effect of chemotherapy in a stroma-rich 3D spheroid model." (PMID 31911892, 2020). "Here, the authors demonstrate that the dual-targeting of VEGF and PDGF is required for targeting resistant FGF2+ tumors which depend on the recruitment of pericytes on tumor microvessels." (PMID 32709869, 2020). "FGF2 is a tumor cell survival factor that is exported from cells by an ER/Golgi-independent secretory pathway." (PMID 32214225, 2020). "FGF2 in the tumor microenvironment plays a key role in regulating cancer stem-like cells (CSCs), promoting the occurrence and development of tumors." (PMID 33381388, 2020). "To identify the sources of FGF2, we performed flow cytometry analysis for FGF2 on cells isolated from the tumour." (PMID 32792542, 2020). "FGF2 signaling regulates normal tissue development, angiogenesis, and wound healing and FGF2 promotes tumor progression, metastasis, and/or angiogenesis in BCa and PCa." (PMID 31959131, 2020). "This process is only partially supported by factors such as VEGF, fibroblast growth factor-2 (FGF-2), and metalloproteinases (MMPs), which are directly secreted by the tumor cells." (PMID 32508920, 2020). "We observed an increase in FGF2 following irradiation of tumours in mice similar to those described in several clinical reports." (PMID 32792542, 2020). "Altogether, our data illustrate that interruption of FGF2-mediated signaling is highly effective against tumor cells exhibiting IM-induced activation of the autocrine FGF2/FGFR loop." (PMID 32599808, 2020). "This enforces the concept that FGF2 mediates tumour growth through alteration of TAMs, both dependent and independent of adaptive immunity." (PMID 32792542, 2020). "Consistent with the antitumor effect, anti-VEGF and imatinib combination effectively suppressed tumor cell proliferation in FGF-2− fibrosarcomas." (PMID 32709869, 2020). "Another report indicated that miR-936 suppressed the tumor aggressiveness by inactivating the PI3K/AKT pathway via repressing FGF2 expression in epithelial ovarian cancer." (PMID 32684842, 2020). "It is noteworthy that the FGF2 secreted by CAFs triggered PR-mediated responses in tumor cells towards the stimulation of cell proliferation." (PMID 33081025, 2020). "We found that fibroblast growth factor-binding protein (FGFBP1) was the carrier molecule of FGF2, which was first found in tumor cell lines." (PMID 33381388, 2020). "In summary, the high expression of FGF2 was related to the tumor size of ESCC tissues and lymph node metastasis; the FGFR3 expression was associated with tumor differentiation, race, and lymph node metastasis." (PMID 33381388, 2020). "In this study, we demonstrated that activation of the FGF2 signaling pathway is a conserved mechanism for acquired resistance to anti-VEGF therapy in two mouse tumor models." (PMID 32076044, 2020).
tumor (continued). "FGF-2 has been shown to be important in tumor angiogenesis, but its role in CNV has been less well studied." (PMID 32143276, 2020). "The extent of the additional effect of the anti-FGF2 antibody correlated with the extent of the tumour response to radiation alone." (PMID 32792542, 2020). "Several studies have shown that FGF-2 is a key cancer-promoting factor in the tumor microenvironment, regulating cross-talk between epithelial and stromal tumor compartments." (PMID 32456056, 2020). "The ability of IM to activate FGF2-mediated signaling in IM-resistant GISTs was revealed in vivo by using xenograft models and by assessing the expression of FGF-2 in tumor specimens of GIST patients who received IM-based therapy." (PMID 32599808, 2020). "Mice whose tumours received radiation reached endpoint 12 days post-irradiation, while the addition of anti-FGF2 antibody led to a significant growth delay with mice reaching the experimental endpoint on average 24 days post-irradiation." (PMID 32792542, 2020). "Our findings reveal the key role that intercellular FGF2 signaling between pericytes and endothelial cells plays in maintaining the tumor vasculature in anti-VEGF therapy–resistant tumors." (PMID 32076044, 2020). "FGF2-mediated tumor resistance to a broad spectrum of chemotherapeutic drugs with diverse structures and mechanisms of action is also well-documented." (PMID 32599808, 2020). "Both simvastatin treatment and PTTG1 knockdown significantly attenuated the expression of c-Myc, FGF-2, and cyclin D3 and increased p21 expression, implicating that simvastatin exerts anti-tumor effects through suppressing PTTG1 function in MDA-MB-231 cells." (PMID 33250768, 2020). "Studies have shown that FGF2 secretion by neutrophils in the tumor microenvironment can promote angiogenesis in metastatic liver tumors." (PMID 32993787, 2020). "In the low-level tumor samples, the middle- to high-level FGF2 was related to cancer with a low progesterone receptor A isoform than B isoform ratio." (PMID 32775417, 2020). "In this study, we show that FGF-2 displays a robust effect on remodeling tumor microvasculatures by increasing perivascular contents and coverage." (PMID 32709869, 2020). "Combination treatment of in vivo tumours with fractionated radiation and a blocking antibody to FGF2 prolongs tumour growth delay, increases long-term survival and leads to a higher iNOS+/CD206+ TAM ratio compared to irradiation alone." (PMID 32792542, 2020). "In turn, CAFs dampen the anti-viral response within tumor cells by secreting high levels of fibroblast growth factor 2 (FGF2)." (PMID 33086754, 2020). "In some cases PTX3 acts as tumor suppressor, inhibiting the proliferation and angiogenesis of FGF2-mediated tumor cells, as well as the epithelial-to-mesenchymal transition (EMT) and its metastatic potential." (PMID 32345771, 2020). "Here we show that FGF2 in the tumour microenvironment can be a potent factor in directing macrophages towards a more pro-tumourigenic state." (PMID 32792542, 2020). "Collectively, these findings suggest that TAMs in the tumour microenvironment are ready to engage with FGF2 in the irradiated tumour microenvironment leading to reprogramming to generate a more pro-tumourigenic milieu." (PMID 32792542, 2020). "In both irradiated and unirradiated tumours FGF2 staining was noted in most F4/80+ macrophages, further suggesting that TAMs are a major source of FGF2." (PMID 32792542, 2020). "In conclusion, these results indicated that these five risk genes (CD19, FGF2, MAP4K1, DCN and STAT6) were actually differentially expressed between normal kidney samples and ccRCC tumour samples." (PMID 31782902, 2020). "FGF-2 exerts its effects on endothelial cells via a paracrine signaling after being released by tumor and stromal cells or mobilized from extracellular matrix." (PMID 31690961, 2020).